PAX7 (paired box 7)
Diseases named in the same sentence as PAX7 in open-access papers (continued):
Sharing a sentence is not in itself a finding about the gene and the disease.
orofacial cleft (3 papers, 2019 to 2024). A disorder of facial skeleton that is characterized by cleft lip and/or cleft palate that result in feeding, speech and hearing problems caused by failures during development. "Pax7 and Pax9 have been linked to orofacial clefts in mice models and different human studies." (PMID 38227085, 2024). "The PAX7 locus has shown genome-wide association in two previous studies, and rare, potentially pathogenic variants located in or near PAX7 have been reported in patients with orofacial clefting." (PMID 31817908, 2019). "Studies have shown that PAX7 plays an essential role in neural crest cell development and, in case of impaired function, could lead to orofacial clefts." (PMID 38227085, 2024). "Transcription factors paired box 7 and 9 (PAX7, PAX9) and receptor-like tyrosine kinase (RYK) have been previously associated with the formation of orofacial clefts but their exact possible involvement and interactions in the tissue of specific cleft types remains uncertain." (PMID 34684112, 2021). "Multiple different cleft candidate gene interactions and mutations have been associated with the development of craniofacial clefts, for example, the involvement of paired box (PAX) genes such as PAX7 and PAX9 in some orofacial cleft cases." (PMID 34684112, 2021).
pancreatic cancer (3 papers, 2015 to 2016). "Pax7 was also shown to be dysregulated in muscle biopsies of patients with pancreatic cancer." (PMID 26856534, 2016).
progeria (3 papers, 2020 to 2021). "Systemic OSKM induction has been shown to mitigate the decline of Pax7+ cells in progeria mice after 6 weeks of cyclic induction of OSKM8." (PMID 34035273, 2021). "Most notably, NANOG decreased the prevalence of SA-β-Gal–positive myogenic progenitors and restored the number of these Pax7+ progenitors in the skeletal muscle of LAKI progeria mice in vivo." (PMID 34516892, 2021).
synovial sarcoma (3 papers, 2021 to 2025). "Cre/LoxP-driven mouse synovial sarcoma (SS) most readily forms in a Myf5-expressing skeletal muscle-specific lineage, whereas fusion oncogene expression in early myogenic precursors (Pax3/Pax7) was fatal and myofiber expression (Myf6) caused myopathy." (PMID 38916046, 2024).
teratoma (3 papers, 2020 to 2021). A non-seminomatous germ cell tumor characterized by the presence of various tissues which correspond to the different germinal layers (endoderm, mesoderm, and ectoderm). "In in vivo developing Pax7−/− teratomas, however, the levels of Myod1 and Myog were significantly lower, as compared to wild type control." (PMID 34571854, 2021). "The levels of mRNAs coding myosin heavy chain isoforms were significantly lower in Pax7−/− teratomas." (PMID 32552916, 2020). "The differences between Pax7−/− and Pax7+/+ teratomas in fiber area were, however, greater in the case of NMJpos fibers." (PMID 32552916, 2020). "The levels of Myf5 and Cdh15 mRNA and proteins were lower in Pax7−/− teratomas, what indicates abnormal formation or maintenance of satellite cell population." (PMID 32552916, 2020). "It is also possible that decreased number of satellite cells in muscle tissue of Pax7−/− teratomas impacts the innervation." (PMID 32552916, 2020). "Together, these findings show that cells at earlier stages of myogenic differentiation dominate in Pax7−/− teratomas, as compared to Pax7+/+ teratomas." (PMID 32552916, 2020). "Next, the proportion of Myf5+ cells localized within the satellite cell niche, calculated as a the percentage of all nuclei in the muscle tissue area, was significantly lower in Pax7−/− teratomas in comparison to Pax7+/+ teratomas." (PMID 32552916, 2020). "Analysis of neurofilament immunoreactivity at low magnification showed that in Pax7−/− teratomas this protein was located in separated clusters while in Pax7+/+ teratomas neurofilament formed long bundles amid myofibers (left column)." (PMID 32552916, 2020). "In Pax7−/− teratoma muscles, significantly less satellite cells were detected, as compared to control tissue." (PMID 32552916, 2020). "The level of mRNAs encoding Pax3 was significantly higher, while the expression of Nfix, Eno3, Mck, Mef2a, and Itga7 was significantly lower in Pax7−/− teratomas, as compared to Pax7+/+ ones." (PMID 32552916, 2020). "Western blot analysis revealed that Myf5 and M-cadherin protein levels were also significantly reduced in Pax7−/− teratomas." (PMID 32552916, 2020). "Myofibers and NMJ were also analyzed in control and Pax7−/− teratoma sections using an anti-skMyh antibody and BTX." (PMID 32552916, 2020). "Pax3 level was slightly higher and Myogenin level was slightly lower in Pax7−/− teratomas than in Pax7+/+ teratomas." (PMID 32552916, 2020). "The weight of Pax7−/− teratomas was approximately two times higher than that of Pax7+/+ teratomas, what supported our earlier observations showing that lack of functional Pax7 increases the proliferation of differentiating ESCs." (PMID 32552916, 2020). "Lama4 expression was on the same level in both types of teratomas, whereas Lama5 and Lamb2 expression was significantly lower in Pax7−/− teratomas." (PMID 32552916, 2020). "Nanog mRNA expression, as well as the level of mesoderm marker T, encoding Brachyury, was much higher in Pax7−/− teratomas in comparison to Pax7+/+ teratomas." (PMID 32552916, 2020). "Myofibrils present in Pax7−/− teratomas were similar to that observed in immature myofibers formed after prepubertal satellite cell ablation." (PMID 32552916, 2020). "The level of mRNAs encoding Pax3 was significantly higher, while the expression of Nfix, Eno3, Mck, Mef2a, and Itga7 was significantly lower in Pax7−/− teratomas, as compared to Pax7+/+ teratomas." (PMID 32552916, 2020). "Analysis of skeletal muscle myosin heavy chain (skMyh) localization showed that in Pax7−/− teratomas the skMyh+ area was reduced in comparison to Pax7+/+ teratomas." (PMID 32552916, 2020). "On the other hand, the levels of mRNAs coding the fetal myoblast markers were lower in Pax7−/− teratomas." (PMID 32552916, 2020). "We also visualized immature myofibers characterized by smaller diameter, centrally located nuclei and less organized contractile bundles in Pax7−/− teratoma muscles." (PMID 32552916, 2020).
teratoma (continued). "Molecular characteristic of skeletal muscles revealed that the levels of mRNAs coding Myh isoforms were significantly lower in Pax7−/− teratomas." (PMID 32552916, 2020). "Altogether, Sprouty1, Pax7, and cell senescence might contribute to the engraftability of expanded teratoma-derived skeletal myogenic progenitors." (PMID 34798067, 2021). "We proved that the number of satellite cells in Pax7−/− teratomas was significantly reduced." (PMID 32552916, 2020). "However, the proportion of larger, “more mature” NMJpos myofibers (> 20 μm) was significantly decreased in Pax7−/− teratomas." (PMID 32552916, 2020). "Thus, the finding that myofibers (both NMJpos and NMJneg) in Pax7−/− teratomas are characterized by smaller dimension than those generated in control teratomas is a novel observation." (PMID 32552916, 2020). "We assessed the weight and histological structure of Pax7+/+ and Pax7−/− teratomas." (PMID 32552916, 2020). "Interestingly, immunolocalization of laminin, i.e., the main component of skeletal muscle basal lamina, showed disturbances in the arrangement of this protein in Pax7−/− teratomas." (PMID 32552916, 2020). "Importantly, in Pax7−/− teratomas, the area occupied by skeletal muscle was significantly smaller in comparison to Pax7+/+ teratomas (28.9% vs 12.3%)." (PMID 32552916, 2020). "Using teratoma assay, we addressed the question whether Pax7 acts as a “switch” allowing transition from embryonic to fetal myogenesis and whether it is necessary for the maturation of skeletal myofibers." (PMID 32552916, 2020). "In our study, muscles of Pax7−/− teratomas presented very similar phenotype." (PMID 32552916, 2020). "Moreover, histological analysis of Pax7−/− teratomas has shown the presence of immature myofibers, i.e., smaller myofibers with centrally located nuclei." (PMID 32552916, 2020). "However, the area of Myh7 and Myh2a myofibers was significantly lower in Pax7−/− teratomas." (PMID 32552916, 2020). "Analysis of teratoma sections revealed significantly higher number of proliferating cells in the absence of functional PAX7." (PMID 34571854, 2021). "Cell cycle phenotype of Pax7−/− ESCs was also suggested by in vivo analyses of teratomas, e.g., in the absence of functional PAX7 teratoma weight increased." (PMID 34571854, 2021). "Currently, using the teratoma model, we analyzed differentiation of wild type, i.e., Pax7+/+ ESCs (ESC lines B3, B5, B8), and ESCs lacking functional Pax7 gene, i.e., Pax7−/− ESCs (ESC lines B4, AI7.15, T2M4)." (PMID 32552916, 2020). "The difference in engraftability might be due to relative PAX7 expression, as in vitro expansion over eight passages reduced PAX7 levels in adult satellite cells but not in teratoma-derived skeletal myogenic progenitors." (PMID 34798067, 2021).
viral infection (3 papers, 2012 to 2023). "Forty-eight hr after viral infection, cells were fixed, and Pax7+ cells were analyzed by immunofluorescence against Pax7." (PMID 37052079, 2023). "While there was a significant amount of Pax3 and Pax7 protein expression at the beginning of culturing, Pax3 and Pax7 became gradually diminished upon Nkx3.2 and Sox9 viral infection, concurrently with the induction of cartilage genes, which should be consistent with a transdifferentiation process." (PMID 22768305, 2012).
cervical cancer (2 papers, 2013 to 2022). A primary or metastatic malignant neoplasm involving the cervix. "PAX7 is a member of the paired box (PAX) family of transcription factors and is oncogenic in a variety of cancers, including cervical cancer." (PMID 35126391, 2022). "Conversely, it is possible that one or more tumor suppressor genes (PAX7, FBG3, ARH1, NEK2, RGL and ARCH) located on chromosome-1 are involved in the development or progression of cervical cancer." (PMID 23429197, 2013).
congenital hydrocephalus (2 papers, 2016 to 2022). Hydrocephalus that is present at birth. "This indicates that, like compound Pax3/7, heterozygotes that display partially penetrant congenital hydrocephalus, Pax3neo/Δ5 that lack compensatory Pax7 revealed that cranial dysmorphogenesis can be caused via collective Pax3 and Pax7 deficiencies." (PMID 35645295, 2022). "Furthermore, consistent with the overlapping expression pattern of Pax3 and Pax7 in early cranial neuroepithelium, we demonstrated a combinatorial role, as compound Pax3/Pax7 heterozygotes display partially-penetrant congenital hydrocephalus." (PMID 26949601, 2016).
developmental delay (2 papers, 2023 to 2025). "Our data reveal a developmental delay in DMD organoids, with a significantly higher proportion of embryonic myotubes and reduced PAX7+ progenitor pools (WT1: 48.49% vs. DMD1: 24.91%)." (PMID 40643552, 2025).
dystroglycanopathies (2 papers, 2016 to 2025). "Nevertheless, our data consistently demonstrated a decreased number of PAX7+ cells in D233E patients, compared with healthy and disease controls, including secondary dystroglycanopathies." (PMID 27807076, 2016).
dystrophin deficiency (2 papers, 2021 to 2023). "Contrary to lower percentages of PAX7- and MYOD1-positive nuclei in DMD-R3381X cultures, these results suggest that dystrophin deficiency may have an effect on translation of PAX7 and MYOD1 or as yet unidentified mechanisms, although this will require further investigation." (PMID 34516770, 2021). "In the case of dystrophinopathies, Pax7 cannot address the lack or complete absence of dystrophin." (PMID 37685856, 2023).
fibrosis (2 papers, 2015 to 2025). the formation of excess fibrous connective tissue in an organ or tissue in a reparative or reactive process. "WGA remained constant across all experimental conditions, suggesting that there is no increase in fibrosis with wheel running or satellite cell depletion in adult female Pax7/DTA mice." (PMID 26579218, 2015).
Hydrocephalus (2 papers, 2016 to 2021). Hydrocephalus is an active distension of the ventricular system of the brain resulting from inadequate passage of CSF from its point of production within the cerebral ventricles to its point of absorption into the systemic circulation. "Of clinical significance, we show that simultaneous heterozygous mutation of Pax7, a Pax3 paralog, induces hydrocephalus in compound heterozygous Pax3/Pax7 mice." (PMID 26949601, 2016). "Moreover, via use of Pax3/Pax7 compound heterozygous mutations, we provide the first experimental mouse data to link the combinatorial mutation of Pax3 and Pax7 to occurrences of congenital hydrocephalus." (PMID 26949601, 2016). "While Pax7 systemic deletion does not cause NC-associated defects, it does exhibit overlapping expression, and Pax3-Pax7 compound heterozygous mice develop hydrocephalus, suggesting combinatorial function." (PMID 34355692, 2021). "Favoring the theory that hydrocephalus is an outcome of multifactorial risks, only ~40% of compound Pax3+/Δ5/Pax7+/Δ2 mutants develop hydrocephalus." (PMID 26949601, 2016). "As Pax3flox/flox/Pax7−Cre mutants exhibit hydrocephalus similar to Pax3flox/flox/Wnt1-Cre mutants, we examined Pax3 and Pax7 proteins." (PMID 26949601, 2016). "Interestingly, our observation that simultaneous Pax7 heterozygous mutation increases the frequency of hydrocephalus may imply that mutation or polymorphism of PAX7, leading to loss of function or reduction of PAX7, might be an important genetic contributory factor to the etiology of hydrocephalus." (PMID 26949601, 2016). "However, examination of coronal sections at P20 (n = 0/30) did not reveal any anomalies indicative of hydrocephalus, suggesting that overlapping and earlier expressed Pax3 can functionally compensate for loss of Pax7 during third ventricle development." (PMID 26949601, 2016). "Pathogenesis of Pax3+/Δ5/Pax7+/Δ2 mutant hydrocephalus is grossly and anatomically indistinguishable from that observed in Pax3flox/flox; Wnt1-Cre and Pax3flox/flox/Pax7−Cre mutants." (PMID 26949601, 2016).
leiomyosarcoma (2 papers, 2021 to 2024). An uncommon, aggressive malignant smooth muscle neoplasm, usually occurring in post-menopausal women. "The concomitant loss of PTEN and PAX7 gave rise to smooth-muscle-like tumors that lie along a spectrum of smooth myogenic differentiation from benign smooth-muscle-like tumors to those that appear like leiomyosarcoma." (PMID 34535684, 2021). "In FN-RMS, expression of Pax7 is necessary for maintenance of the skeletal muscle identity as knock-out (KO) of Pax7 in FN-RMS mouse models results in tumors that display smooth-muscle morphology, consistent with leiomyosarcoma." (PMID 39902277, 2024). "Strikingly, these Pten;Pax7 deleted tumors were no longer FN-RMS but displayed smooth muscle differentiation similar to leiomyosarcoma." (PMID 34535684, 2021).
muscle atrophy (2 papers, 2024 to 2025). "Of note, the data from our experiments show reduced expression of PAX7-positive cells in both models of skeletal muscle atrophy, suggesting that the available pool of satellite cells decreased after 10 days since receiving the regenerating stimulus." (PMID 38892242, 2024).
Obesity (2 papers, 2023 to 2025). Accumulation of substantial excess body fat. "At 7 dpi, obesity attenuated mRNA expression of muscle regenerating markers, MyoD, and tended to decrease Pax7 and Myogenin expression." (PMID 36513394, 2023). "PAX7 expression was significantly decreased in individuals with obesity compared to lean controls." (PMID 40127780, 2025). "Individuals with obesity showed significantly elevated CS markers, along with reduced expression of GLUT4 and PAX7, indicating impaired insulin action and regenerative potential." (PMID 40127780, 2025).
osteosarcoma (2 papers, 2009 to 2021). A usually aggressive malignant bone-forming mesenchymal neoplasm, predominantly affecting adolescents and young adults. "Pax3 has also been reported to be unable to initiate myogenesis in the human Saos-2 osteosarcoma cell line and mouse endothelial cells line BEND3, and Pax7 is unable to activate myogenesis in the C3H10T1/2 multipotent mesenchymal cell line." (PMID 19221588, 2009).
scoliosis (2 papers, 2022 to 2023). A congenital or acquired spinal deformity characterized by lateral curvature of the spine. "More recently, four loss-of-function variants mapping within PAX7 exons 1–3 have been linked to a myopathy with congenital onset and autosomal-recessive inheritance, referred to as progressive congenital myopathy with scoliosis (MYOSCO; OMIM: 618578)." (PMID 34740639, 2022). "However, some muscle diseases originate from genetic alterations impinging directly on satellite cell function and their ability to repair/regenerate myofibres, such as mutations in PAX7 causing Progressive congenital myopathy with scoliosis (MYOSCO; OMIM: 618578)." (PMID 34740639, 2022). "This led to increased muscle fiber size, rescue of most muscle fiber type alterations, normalization of the satellite cell marker Pax7 levels, increased grip strength, reduced fibrosis, and decline in scoliosis in Myh3 knockout mice." (PMID 37492882, 2023).
Sepsis (2 papers, 2019 to 2025). Sepsis is defined as life-threatening organ dysfunction caused by a dysregulated host response to infection. "Whereas the number of PAX7-positive muscle satellite cells was unaffected by illness, gene expression of proliferation marker Pcna was clearly increased by sepsis, especially with PN+3-HB." (PMID 31262340, 2019). "In TA, sepsis increased expression of markers of muscle regeneration Myf5 and Myog, but not Pax7 and Myod1." (PMID 41385533, 2025).
adenoma (1 paper, 2016). A neoplasm arising from the epithelium. "Both, Pax7 (P < 0.005) and Sox2 (P < 0.001) were significantly enriched in CD15high adenomas when compared to CD15low tumors." (PMID 27894339, 2016).
Alzheimer disease (1 paper, 2023). A progressive, neurodegenerative disease characterized by loss of function and death of nerve cells in several areas of the brain leading to loss of cognitive function such as memory and language. "Alzheimer’s disease in A-C group was accompanied with decreased number of Pax7 positive cells in the gastrocnemius muscle compared to the H-C group (p < 0.001)." (PMID 36781881, 2023).
autoimmune myasthenia gravis (1 paper, 2025). "In the muscle and blood of myasthenia gravis patients, significantly increased circFBL has been shown to act as a sponge for miR-133, thereby upregulating PAX7 (Paired Box 7), a key transcription factor for muscle stem cell specification and proliferation." (PMID 41322400, 2025). "Overexpression of circFBL was found to promote myoblast proliferation through this circFBL/miR-133/PAX7 axis in experimental autoimmune myasthenia gravis mice models." (PMID 41322400, 2025).
cerebral palsy (1 paper, 2020). A group of disorders affecting the development of movement and posture, often accompanied by disturbances of sensation, perception, cognition, and behavior. "In both typically developing (TD) children and patients with cerebral palsy (CP), SCs were identified on muscle sections through their co-expression of both PAX7 and CD56 markers." (PMID 32848872, 2020).
CHARGE syndrome (1 paper, 2024). CHARGE syndrome is a multiple congenital anomaly syndrome characterized by the variable combination of multiple anomalies, mainly Coloboma; Choanal atresia/stenosis; Cranial nerve dysfunction; Characteristic ear anomalies (known as the major 4 C's). "Furthermore enh-C has a conserved and active counterpart in human, and pathogenic variants of PAX7 have recently been shown to affect craniofacial development, a phenotypic feature of CHARGE syndrome." (PMID 39418292, 2024).